PTPN11 (protein tyrosine phosphatase non-receptor type 11)
Diseases named in the same sentence as PTPN11 in open-access papers (continued):
Sharing a sentence is not in itself a finding about the gene and the disease.
Noonan syndrome (continued). "Diseases associated with mutations in PTPN11 include NS and Noonan syndrome with multiple lenses (NS-ML)." (PMID 36760995, 2023). "Germline alterations of PTPN11 are associated with Noonan syndrome (NS), the most frequent dysfunctional growth syndrome." (PMID 36973520, 2023). "Recurrent germline PTPN11 mutations in exons 3 and 13 are associated with Noonan syndrome (NS) characterised by multiple congenital anomalies." (PMID 36882706, 2023). "50% of Noonan syndrome is associated with missense variants in PTPN11, resulting in abnormalities in both the N‐SH2 and PTP functional domains are abnormal." (PMID 37525886, 2023). "The protein product encoded by PTPN11, SHP‐2, plays a key role in the embryonic development of heart valves, which is consistent with the high prevalence of valve lesions in Noonan syndrome." (PMID 37525886, 2023). "Approximately 50% of Noonan syndrome is caused by functionally acquired missense variants in the PTPN11 gene." (PMID 38075692, 2023). "Specific genes have been found to be associated with Noonan syndrome, with PTPN11 being the gene associated with about half of the cases, which has also previously been associated with bilateral coronary artery dilation in Noonan syndrome." (PMID 36593444, 2023). "In one patient, in addition to the somatic TEK mutation found in VA biopsy, a germline PTPN11 mutation causing Noonan syndrome was detected." (PMID 37380669, 2023). "Germline variants of PTPN11 cause Noonan syndrome 1 (OMIM# 163950) and LEOPARD syndrome 1 (OMIM# 151100)." (PMID 36864519, 2023). "Germline mutations in the human PTPN11 gene have been associated with Noonan syndrome and with Noonan syndrome with multiple lentigines (formerly known as LEOPARD syndrome), two multisystem developmental disorders." (PMID 38129686, 2023). "Most germline PTPN11 variants in patients with Noonan syndrome are located at the interaction site, disrupting autoinhibition with gain-of-function mutations." (PMID 36864519, 2023). "Mutations in SHP2, encoded by the PTPN11 gene, cause Noonan syndrome (NS) and Noonan syndrome with multiple lentigines (NSML)." (PMID 33689087, 2022). "A bona fide JMML is seen in 3% of children with PTPN11 mutated Noonan syndrome, often with an excess of blasts and very severe neonatal manifestations, half of patients dying in the first month of life." (PMID 35819517, 2022). "A transient JMML-like myeloproliferative disorder is seen in 2.5–10% in infants with Noonan syndrome, almost invariably harboring a germline PTPN11 mutation." (PMID 35819517, 2022). "PTPN11 activating mutations were always found in Noonan syndrome patients, and it is known that PTPN11 activating mutation always causes leukemia, such as JMML, AML, or ALL." (PMID 35756991, 2022). "Mutations in the PTPN11 gene can lead to various phenotypes, including Noonan syndrome and LEOPARD syndrome." (PMID 36186652, 2022). "A broad spectrum of heterozygous germline activating mutations in the tyrosine phosphatase SHP2 encoded by PTPN11 has been found to cause Noonan syndrome (NS), a dominantly inherited developmental disorder from the RASopathy group affecting 1:1500 individuals." (PMID 35535491, 2022). "PTPN11 gene, which codes for SHP2, can be mutated in patients with Noonan Syndrome, an autosomal dominant RASopathy, characterized by cardiac, endocrine, neurodevelopmental and hematologic disorders." (PMID 36284306, 2022). "Mutations in PTPN11 are well characterised in children with Noonan syndrome and juvenile myelomonocytic leukaemia." (PMID 36357925, 2022). "Constitutional gain-of-function mutations of PTPN11 cause Noonan syndrome in humans as a result of the activation of RAS signaling." (PMID 35625983, 2022). "PTPN11 heterozygous gain-of-function mutations or duplications cause Noonan syndrome 1 (OMIM: 163950)." (PMID 35806420, 2022).
Noonan syndrome (continued). "We focused on PTPN11 (HGNC:9644) Exon 3 that contains 30 different PTPN11 Noonan syndrome (NS) mutation sites." (PMID 36349709, 2022). "There is one case in the literature describing an intraventricular subependymoma in a patient with Noonan Syndrome and a germline mutation in PTPN11." (PMID 35484611, 2022). "Mutation frequency heat map of spontaneous PTPN11 variants show spatial clustering in the testis due to germline selection explaining the high birth incidence of Noonan syndrome." (PMID 36349709, 2022). "Germline mutations in PTPN11 cause Noonan syndrome, the clinically related LEOPARD syndrome (LS), and leukemogenesis." (PMID 36605987, 2022). "Since the discovery of PTPN11 mutations as the cause of Noonan syndrome in 2001, a plethora of preclinical research has been performed in order to better define the pathological mechanisms of the disease and establish potential drug targets." (PMID 36407105, 2022). "It is initially found that PTPN11 mutation induces SHP2 activation, leading to Noonan syndrome and juvenile leukemia." (PMID 35061863, 2022). "In two other cases, Noonan syndrome was identified by heterozygous variants in the PTPN11 gene and the RIT1 gene, respectively." (PMID 35160154, 2022). "One child had Noonan syndrome with a prenatally confirmed pathogenic PTPN11-gene (OMIM #176876) variant." (PMID 34733861, 2021). "Mutations in PTPN11, which encodes SHP2, cause “rasopathies” and are found in about 50% of patients with Noonan syndrome." (PMID 35582302, 2021). "In one further child (P35) additional genetic testing confirmed a PTPN11 pathogenic variation causing Noonan syndrome." (PMID 34325699, 2021). "Of note, 3 out of 21 (14%) unrelated parents were found to be candidate somatic mosaic for the PTPN11 pathogenic variants causative for Noonan syndrome, with an average VAF percentage measured by amplicon NGS of 0.3%." (PMID 34930489, 2021). "Genetic studies have linked ~50% of Noonan syndrome to mutations in PTPN11 gene, which encodes SHP-2 protein, an SH2 domain-containing, non-receptor tyrosine phosphatase (PTPase) essential for cellular proliferation, differentiation, and migration." (PMID 34568467, 2021). "Correlation analysis showed that PTPN11 patients with Noonan syndrome have higher prevalence of Factor XII deficiency (r = 0.56, p = 0.03)." (PMID 34857025, 2021). "Noonan syndrome is attributed to germline mutations of Ptpn11 that affect the SHP2 phosphatase domains." (PMID 34746416, 2021). "Only one study aimed at analyzing neurodevelopment using iPSCs from three patients diagnosed with Noonan syndrome (NS-iPSCs) harboring mutations in PTPN11." (PMID 34828352, 2021). "PTPN11 mutations are associated with both bone and cartilage manifestations in patients with Noonan syndrome (NS) and metachondromatosis (MC), although the underlying mechanisms remain elusive." (PMID 33500396, 2021). "As previously stated, mutations in the PTPN11 gene are present in more than 50% of patients with Noonan syndrome." (PMID 34344467, 2021). "In case of Noonan syndrome (NS) characterized by germline PTPN11 mutations, studies which have derived hiPSCs from hematopoietic cells and which harbor the PTPN11 mutations were found to successfully recapitulate features of NS." (PMID 34571968, 2021). "Germline PTPN11 mutations are responsible for approximately 40–50% of Noonan syndrome cases, leading to a unique phenotypic association between the two syndromes." (PMID 34488904, 2021). "Noonan syndrome with multiple lentigines is an autosomal dominant disorder caused by pathogenic variants in PTPN11, RAF1, BRAF, and MAP2K1." (PMID 38835701, 2021). "In our cohort, we identified only a mutation (G60S) in PTPN11 reported as pathogenic in Noonan syndrome in one patient." (PMID 32164600, 2020). "Most forms are autosomal dominant, with PTPN11 accounting for over half of Noonan syndrome patients, and many genes are associated with multiple RASopathies." (PMID 32733828, 2020).
Noonan syndrome (continued). "A wide phenotypic variability and genetic heterogeneity have also been described in individuals with Noonan syndrome in relation to rare variants in PTPN11." (PMID 33226994, 2020). "Three individuals had mutations in PTPN11 indicating Noonan syndrome, and 1 had a TRPV4 mutation associated with brachyolmia type 3, an autosomal dominant skeletal disorder." (PMID 32939436, 2020). "Mutations in the PTPN11 gene that codes for the SHP2 protein have been observed in Noonan syndrome; these mutations cause an overactivation of SHP2 and are associated with hyperactivation of the extracellular-signal-regulated kinase (ERK1/2) pathway." (PMID 33076315, 2020). "Here, we show that even in the general population, common and rare variants in PTPN11 are independently associated with phenotypes such as hypothyroidism, small birth weight and low percent of body fat observed in some cases of Noonan syndrome." (PMID 33226994, 2020). "Using WES and Sanger sequencing, we discovered that the patient carried the common pathogenic PTPN11 variant (c.A922G p.N308D) of Noonan syndrome." (PMID 32054441, 2020). "The majority of Noonan syndrome is caused by mutations of the PTPN11 gene accounting for about 50% of the cases." (PMID 32396283, 2020). "Noonan syndrome is caused by mutations in PTPN11 and part of a group of related disorders arising from activating mutations in RAS-MAPK signaling pathway known as RAS-opathy which display many phenotypes across a variety of organ systems." (PMID 33226994, 2020). "PTPN11 (or SHP-2) is a tyrosine phosphatase adaptor protein within the RAS/MAPK pathway known to cause Noonan syndrome." (PMID 32164789, 2020). "In particular, skeletal dysplasias (ACAN, MMP13 mutations) and Noonan syndrome (PTPN11) were detected." (PMID 32939436, 2020). "In terms of disease initiation, inherited germline mutations in PTPN11 are associated with Noonan syndrome, where patients have increased risk of cancer development." (PMID 33053751, 2020). "Worldwide a number of molecular studies have shown involvement of PTPN11 in causation of Noonan syndrome (NS)." (PMID 32164556, 2020). "The PTPN11 gene is the most implicated gene in Noonan syndrome (61%), followed by SOS1 and RAF1 genes (15 and 6%, respectively)." (PMID 31030682, 2019). "Here, we report the first case of an 11-year-old Thai boy with Noonan syndrome who presented with symptoms related to hydrocephalus secondary to subependymoma in the fourth ventricle, and PTPN11 mutation was identified in this patient." (PMID 31637070, 2019). "Different mechanisms of disease have been demonstrated to be associated with the two classes of PTPN11 mutations underlying Noonan syndrome and Noonan syndrome with multiple lentigines (also known as LEOPARD syndrome)." (PMID 31277675, 2019). "For example, studies of Noonan Syndrome-associated cardiac defects reveal that hypertrophic cardiomyopathy is observed in less than 20% of cases linked to PTPN11/SHP2 or SOS1 mutations, but greater than 90% of RAF1 mutations." (PMID 31017896, 2019). "PTPN11 mutations in LS are loss-of-function mutations, while those in Noonan Syndrome are gain-of-function mutations." (PMID 31722741, 2019). "Those include the Noonan syndrome and the Leopard syndrome with inherited mutations of the PTPN11 gene." (PMID 30108215, 2018). "The group included four patients with Noonan syndrome, three with heterozygous mutations of the PTPN11 gene, and one with an SOS1 mutation." (PMID 30541462, 2018). "Germline gain-of-function mutations of PTPN11 cause ~50% of the cases of the genetic disease Noonan Syndrome, a disorder that causes abnormal development in different parts of the body and is associated with the increased risk of malignancy and leukemia." (PMID 30208623, 2018).
Noonan syndrome (continued). "In biopsy 4D25, PTPN11 c.1504T > A (p.Ser502Thr – Noonan syndrome) was called as a single-nucleotide variant, but on validation, it was identified as a double-nucleotide substitution c.1504_1505delTCinsAA (p.Ser502Lys)." (PMID 30355600, 2018). "The large number of different de novo variants is consistent with epidemiological data that concur that PTPN11-associated Noonan syndrome mutations have a high spontaneous birth prevalence (about one in 10,000 births)." (PMID 30355600, 2018). "Intriguingly, activation of Shp2 induced by PTPN11 mutations leads to development of Noonan syndrome and juvenile leukemias." (PMID 28085101, 2017). "PTPN11 mutations cause approximately 50% of Noonan syndrome, an autosomal dominant disorder associated with several congenital cardiac defects, including pulmonary stenosis, hypertrophic cardiomyopathy, and atrioventricular septal defects." (PMID 28228731, 2017). "In contrast with SETBP1 mutations, germline PTPN11 mutations causative for Noonan syndrome rarely overlap with somatic mutations observed in leukemia." (PMID 28346496, 2017). "PTPN11 mutations are most commonly associated with Noonan syndrome and juvenile myelomonocytic leukemia; however, activating somatic mutations have been observed in solid tumors, including colorectal, breast, and renal cell carcinomas." (PMID 29383146, 2017). "About half of patients with Noonan syndrome harbor a germline activating mutations of the protein tyrosine phosphatase src homology-2 domain containing protein tyrosine phosphatase (SHP2) (encoded by PTPN11), a positive regulator of the RAS signaling pathway." (PMID 28829353, 2017). "SHP2, encoded by PTPN11, is a first identified oncogenic tyrosine phosphatase that been linked to several genetic, developmental diseases such as Noonan syndrome and multiple cancers including leukemia, lung, and breast cancer, and neuroblastoma." (PMID 29371942, 2017). "Nearly 90% of the LEOPARD syndrome cases and 45% of Noonan's syndrome cases are caused by missense mutations in PTPN11 encoding the SHP2 tyrosine phosphatase." (PMID 27110425, 2016). "In the case of Noonan syndrome, gain-of-function missense mutations in PTPN11 account for 50% of all cases, whereas mutations in other components of the Ras/MAPK pathway (KRAS, SOS1 and RAF1) cause the remainder." (PMID 26935104, 2016). "We previously measured the germline frequencies of the PTPN11 c.922A>G Noonan syndrome disease mutation in 192 testis pieces (32 pieces in each of 6 slices comprising an entire testis) by targeting this nucleotide with PAP, a version of allele-specific PCR." (PMID 27341568, 2016). "It is interesting to note that TCEAL1 has been shown to interact with PTPN11, the causative gene for Noonan syndrome characterized by short stature, craniofacial anomalies, pectus deformities, webbed neck and sometimes ID." (PMID 27506666, 2016). "There is also an association between Noonan syndrome (a neuro-cardio-facial-cutaneous syndrome) characterized by germ-line mutations of MAP kinase pathway genes (PTPN11, SOS1, KRAS, NRAS, RAF1, BRAF, SHOC2 and CBL) and PA (as well as other malignancies)." (PMID 25792358, 2015). "For example, PTPN11, which was found carrying damaged acetylation caused by (T2I) associated with “noonan syndrome 1”, was involved in downstream effectors of cytoplasmic protein tyrosine kinases." (PMID 26495027, 2015). "As an example of our integrative approach, we propose that PTPN11 variants in Noonan syndrome aberrantly activate the protein by disrupting an uncharacterized cluster of phosphorylation sites." (PMID 25611800, 2015). "Germ-line PTPN11 mutations cause ~50% of Noonan Syndrome (NS), which is among the most common autosomal dominant disorders." (PMID 24628801, 2014). "Germline mutations in SHP2 encoding gene PTPN11 are associated with Noonan syndrome, LEOPARD syndrome, and metachondromatosis (18, –, 21)." (PMID 25331952, 2014).
Noonan syndrome (continued). "Germ-line PTPN11 mutations cause about 50% of Noonan Syndrome (NS), which is among the most common autosomal dominant disorders." (PMID 24628801, 2014). "The results add to our understanding of the pathophysiology of skeletal abnormalities observed in humans with germline mutations in the PTPN11 gene (e.g. Noonan syndrome and LEOPARD syndrome)." (PMID 24077964, 2013). "The diagnosis of Noonan syndrome is mainly clinical, with some recent studies showing mutation in the PTPN11 gene to be present in about 50–60% of individuals with Noonan syndrome." (PMID 23691379, 2013). "Ptpn11 is a member of the protein tyrosine phosphatase family, and mutations are identified with Noonan syndrome, one of the most common genetic disorders of congenital heart defects." (PMID 24147020, 2013). "Mutation of PTPN11 in Noonan syndrome and leukaemic cells resulted in gain-of-function enhanced phosphatase activity." (PMID 20700123, 2010). "Exome sequencing followed by Sanger validation in Individual III-2 revealed a de novo pathogenic PTPN11 variant (c.236A>G, p.(Gln79Arg)), consistent with Noonan syndrome, accounting for her history of short stature, pulmonic stenosis, and failure to thrive, but not her CFNS clinical diagnosis." (PMID 40490530, 2025). "Similarly, inhibition of mouse PTPN11 (encoding SHP2, an upstream promotor of MAPK), caused reduced neurogenesis and increased gliogenesis, whereas activation of SHP2 in a mouse model of Noonan syndrome caused increased neurogenesis and decreases astrogenesis." (PMID 40548072, 2025). "PTPN11 gain-of-function mutations (e.g., Noonan syndrome) ablate the autoinhibited binding of the N-SH2 (N-terminal SH2) domain on the PTP, actively creating a situation where SHP2 is constitutively activated with complete freedom from having to rely on upstream signals." (PMID 41462587, 2025). "Patients with syndromic congenital heart disease were screened out at enrolment, but mutations in CHD7 associated with CHARGE syndrome, KMT2D associated with Kabuki syndrome, NSD1 associated with Sotos syndrome, and PTPN11 associated with Noonan syndrome were identified in the study." (PMID 38339013, 2024). "Noonan syndrome is the most prevalent RASopathy, with an estimated incidence of 1 in 2500 live births, and it is typically inherited in an autosomal dominant manner, with 50% of cases involving gain-of-function mutations in the PTPN11 gene." (PMID 39594917, 2024). "Mutations in PTPN11 are linked to Noonan syndrome and acute myeloid leukemia." (PMID 39872609, 2024). "patient with a genetically proven Noonan syndrome due to a PTPN11 mutation." (PMID 38459225, 2024). "The PTPN11 variant conferred a diagnosis of Noonan syndrome." (PMID 39309743, 2024). "Others are caused by point mutations in PTPN11 (Noonan syndrome) and HRAS (Costello syndrome)." (PMID 39459551, 2024). "However, one of the affected siblings had an additional pathogenic variant in PTPN11, associated with Noonan syndrome." (PMID 38298611, 2024). "Additionally, deletion of the gene whose gain of function is associated with the PAE disorder Noonan syndrome, PTPN11, blocks differentiation of early germ cells." (PMID 39459551, 2024). "This might explain male infertility in gain- and loss-of-function mutations in PTPN11 associated with pathological conditions such as Noonan syndrome and LEOPARD syndrome." (PMID 38397181, 2024). "Additionally, variants that reduce PTPN11 activity cause Noonan syndrome with multiple lentigines (NSML), which shares clinical features with NS." (PMID 39596579, 2024).